EGFR (epidermal growth factor receptor)
Diseases named in the same sentence as EGFR in open-access papers (continued):
Sharing a sentence is not in itself a finding about the gene and the disease.
tumor (continued). "To assess the clinical significance of our studies, we investigated the effects of dasatinib treatment and the potential of [89Zr]Zr-cetuximab to monitor changes in EGFR membrane abundance in an EGFR-expressing TNBC PDX tumor model." (PMID 32295603, 2020). "The epidermal growth factor receptor (EGFR) signaling is one of the most commonly deregulated pathways in human tumor." (PMID 32321917, 2020). "This initial work was then extended to using similarly shaped gold nanostars (AuNS) for both in vivo longitudinal PD-L1 and EGFR tracking, as well as ex vivo Raman mapping of whole tumor lesions." (PMID 32545182, 2020). "Depletion of tribbles pseudokinase 3 (TRIB3) is known to suppress the expression of several tumor-promoting factors, including EGFR." (PMID 32694521, 2020). "Target 2, which resided 1.06 mm from target 1, exhibited tumor cells containing both strongly amplified MET and CCND1, 3 to 4 copies of EGFR, 3 to 4 copies of FGFR2, and loss of both copies of the genes encoding PD-L1/PD-L2." (PMID 32338752, 2020). "It is related to tyrosine kinase inhibitor (TKI)-associated drugs, which inhibit the abnormal growth of tumor by reducing the binding of tyrosine kinase with EGFR in the cancer cells." (PMID 33007940, 2020). "In summary, we demonstrate that EGFR/Ras-induced CCL20 is a chemokine with a vital function in tumour–stroma interaction within the tumour micromilieu." (PMID 32601464, 2020). "Epidermal growth factor (EGF)/EGF receptor (EGFR) signaling is a key factor in tumor growth and the development of metastasis, and is considered a target for chemotaxis in cancer therapy." (PMID 32867284, 2020). "Univariate cox regression analysis revealed that 14 genes within the hot subnetworks showed expression pattern significantly correlated with patients’ overall survival, including PTN and EGFR, two major players in tumor progression." (PMID 32231683, 2020). "In contrast, LTTs that use EGF as a targeting moiety avoid the tumor cell activation pathway entirely because they ultimately use EGFR to kill the target cell." (PMID 32630411, 2020). "More importantly, the released cetuximab also bound EGFR expressed on vascular endothelial cells, to damage the vasculature of the tumor." (PMID 32587779, 2020). "In terms of EGFR mutation sites different immunological profiles have been reported with the prevalence of “inflamed” TME consisting of higher level of functional TILs in EGFRL858R samples compared to EGFR exon 19 deletion tumor samples." (PMID 32760402, 2020). "D2C7-IT displayed a high level of killing against tumor cell lines expressing EGFR, EGFRvIII or a mixture of both EGFR/EGFRvIII." (PMID 32957689, 2020). "The EGFR-targeting antibody cetuximab is also used under the prerequisite of wildtype KRAS or BRAF status, as mutations in these oncogenes render tumours insensitive to EGFR-targeted therapy." (PMID 32647253, 2020). "This strategy therefore has the potential to exploit EGFR overexpression in tumours that are otherwise protected from anti-EGFR treatment strategies by reason of their KRAS mutations." (PMID 32913288, 2020). "Epidermal growth factor receptor (EGFR) plays a key role in regulating various intracellular signaling for tumor cell proliferation, differentiation, migration, and invasion." (PMID 33297461, 2020). "The concept of mCAR T cells was tested through generating mCAR T cells targeting EGFR that were activated against EGFR-expressing cells upon exposure to tumor protease." (PMID 32391048, 2020). "When injected in high EGFR-expressing tumor-bearing mice, [18F]AlF-NOTA-PODS-ZEGFR:03115 and [18F]AlF-NODAGA-PODS-ZEGFR:03115 showed similar pharmacokinetics and allowed for clear visualization of the tumors already 1 h post-injection." (PMID 32235296, 2020). "EGFR is not only expressed by tumor cells but also by endothelial cells and the EGF/EGFR pathway participates in processes of tumor vascularization." (PMID 31938054, 2020).
tumor (continued). "Hematoxylin & eosin (H&E) and immunohistochemical (IHC) staining was performed on tumor specimens from every animal to confirm tumor presence and EGFR status." (PMID 33042280, 2020). "Taken together, our study supports interchangeable use of cobas v2 and PANAMutyper in tumor and plasma EGFR testing." (PMID 32224854, 2020). "In order to study the efficacy of new combinatorial treatments involving anti-CTLA-4 and anti-EGFR drugs, we decided to test ipilimumab on a panel of tumor cells with other anti-EGFR specific compounds, such as aptamers." (PMID 32024070, 2020). "The present study demonstrates that the ATF6-mediated production of EGF in SCCs induces the recruitment of vascular endothelial cells and triggers tumor angiogenesis via the activation of the EGFR signaling in vascular endothelial cells." (PMID 32630838, 2020). "EGFR is expressed in normal epithelial cells of the skin, hair follicles or the gastro intestinal tract, but it is also detected in many tumor entities." (PMID 32903756, 2020). "CL4 binding on the cell membrane resulted in antagonism of vascularization and cell adhesion pathways normally regulated by the binding of EGFR to integrin αvβ3, resulting in reduced tumor growth." (PMID 32848740, 2020). "The anomalous activation of the EGFR generate improved proliferation and additional tumor-promoting activities in different types of cancer, including HNC." (PMID 33324546, 2020). "Added together, these results indicated that the preventive TNuF supplement has an additive effect on RT to modulate tumor mitosis and the EGFR pathway." (PMID 32872195, 2020). "Of these biopsies, 95 samples from 25 patients contained adequate tumour and/or DNA content for EGFR and PDGFRA amplification status to be determined successfully through aCGH analysis." (PMID 33120534, 2020). "Increased HB-EGF secretion in HLMFs, which upregulate α-SMA, markedly increases tumor formation of CC cells and tumor invasion in vivo by EGFR activation-mediated upregulation of PECAM-1 and activation of STAT3/ERK." (PMID 32708604, 2020). "We found that in addition to cell cycle regulatory effects, the GEM inhibited tumor growth and angiogenesis by suppressing the epidermal growth factor receptor (EGFR) signaling pathway." (PMID 32111094, 2020). "EGFR is a transmembrane tyrosine kinase receptor that is involved in initiating tumor formation when highly expressed." (PMID 33273921, 2020). "Light was applied 1 h post injection of the EGFR targeted nanobody–PS conjugates, leading to approximately 90% of tumor necrosis and importantly minimal damage to the surrounding normal tissues." (PMID 32977602, 2020). "Its role in the assessment of tumour proliferation was also researched, with a considerable number of studies examining the potential of 18F-FDG in predicting EGFR mutation status in NSCLC patients." (PMID 33198090, 2020). "Two key proteins in cell physiology—CDC42 and EGFR—seem to be central to these pathways, suggesting their relevance for tumor progression to stage 3." (PMID 31945087, 2020). "The bacterial minicells were modified with an EGFR antibody to provide tumor-targeting to the EGFR positive tumors." (PMID 32102476, 2020). "Previous research by the research group found the elevated STAT3 and EGFR in the tumor tissues from HNSCC patients." (PMID 32577124, 2020). "These are short-lived mono- or bispecific molecules, for example against the growth factor EGFR (“epidermal growth factor receptor”), which make the connection between the cytotoxic T-cells and the tumor cells and thus the T lymphocytes to the cancer cells." (PMID 33240813, 2020).
tumor (continued). "Our results indicate similarity in phenotype (growth pattern and EGFR expression) between tumor cell/CAF spheroids and the patient tumors." (PMID 33353547, 2020). "Several pre-clinical data, here reported, showed encouraging results, corroborating c-Src inhibitors capability to overcome tumor resistance to EGFR-inhibitors in different cancer types." (PMID 32517369, 2020). "We also found that the EGFR inhibition of the tumor was related to skin alterations, such as stratum corneum thickness." (PMID 33015988, 2020). "The relationship between EGFR inhibition in skin and in the tumor explains the parallel biological effect." (PMID 33015988, 2020). "Among fly genes, as expected, we observed suppression of the tumor phenotype when components of EGFR pathway are down regulated." (PMID 32737065, 2020). "IFIs are actually considered tumor suppressors and gatekeepers of EGFR mitogenic signalling and antagonists of EGFR-driven tumorigenesis." (PMID 32377505, 2020). "Depletion of TRIB3 results in drastically decreased expression of several tumor-promoting factors, including EGFR, across cancers." (PMID 32694521, 2020). "Recent studies have found that driver mutations (including EGFR and ALK mutations) are highly inconsistent among MPLCs, emphasizing the need to separately analyse gene mutation status in multifocal tumours." (PMID 32690092, 2020). "We found that FOXO3A is less expressed in high-grade malignant tumor cells and is negatively correlated with EGFR expression." (PMID 33224867, 2020). "Engineered anti-EGFR nanobodies with GPI exosomal fusion proteins are transfected into donor cells to target (+) EGFR-tumor cells." (PMID 32957534, 2020). "This miRNA upregulation resulted in the downregulation of EGFR expression in patients with significant tumor regression." (PMID 32580435, 2020). "In the past decade, a new paradigm has emerged, EV translocation of functionally active EGFR and EGFR ligands between tumour cells and local and distant cells, imparting a quasi EGFR amplified phenotype upon the recipient cell." (PMID 33143170, 2020). "Our previous investigations echo other reports describing how resistin and EGFR promote tumor progression through downstream p44/p42 MAPK (ERK1/2) signaling." (PMID 33313320, 2020). "In the nucleus, EGFR plays a key role in transcription by acting as a transcriptional coactivator for genes, which initiate tumor formation such as cyclin D1." (PMID 33273921, 2020). "With the availability of more EGFR TKIs and a better understanding of tumor biology, further prospective studies are warranted to define the optimal treatment approach for uncommon EGFR mutant-positive NSCLC." (PMID 33036377, 2020). "Among twelve protein kinases, EGFR, HER4, and EphA3 were associated with tumor recurrence status, recurrence-free survival (RFS) and overall survival (OS)." (PMID 32093644, 2020). "Although only a small percentage of the trial population had post-treatment tumor analysis (about 10%), this trial was one of the few to attempt confirmation of effects on EGFR." (PMID 33187135, 2020). "The relative expression of EGFR was significantly higher in tumor compared with control [control: 2.20 (1.45-3.70) vs. case: 6.65 (5.00-11.00); pvalue = 7.286 × 10−6]." (PMID 33273921, 2020). "After c38 tumor cell inoculation, significantly less active EGFR, PDGF-Rα and HGF/MSPR receptors were detected in the livers of pLIVE-DCN animals compared to pLIVE-0 mice (p value < 0.05)." (PMID 32824864, 2020). "Of note, human embryonic kidney cells (HEK293) have the lowest expression levels of EGFR among the tested cell lines as compared to RC21, suggesting EGFR as a tumor biomarker or target in RCC." (PMID 32413049, 2020). "The cabozantinib group had an overall DCR of 38%, ORR at week 12 was 10% (six patients confirmed partial response), and 64% of these patients showed tumor regression, including those with KRAS and EGFR mutations." (PMID 32575417, 2020).
tumor (continued). "The EGF/EGFR pathway plays a key role in tumor progression through regulation of proliferation, survival, angiogenesis, invasion, and immune evasion." (PMID 32413973, 2020). "The authors discovered that the enzymatically inactive PEPDG278D silences EGFR-downstream signaling pathways, inhibiting tumor cell proliferation and growth in vivo." (PMID 32824561, 2020). "We demonstrated the tumor-suppressive effect of GA, which induced the decrease of PD-L1 expression through binding to EGFR in NSCLC." (PMID 32204508, 2020). "In NSCLC, for example, EGFR overexpression is correlated with patient histopathological findings, and with the degree of tumor aggression and invasion." (PMID 32742459, 2020). "Because of the deficiency of EGFR expression in AtT-20/D16v-F2 cells and difficulty in obtaining human corticotropinomas cell line, we used a model cell line HLE which delivered EGFR and human primary tumor cells." (PMID 33537004, 2020). "Our data showed that Formo reduced the in vivo tumor growth in both EGFR WT and mutant xenograft tumors." (PMID 32276600, 2020). "A potential drawback of a therapeutic pre-dose, which is approximately 100 times higher than the tracer dose, is that it can partially or irregularly saturate the therapeutic target on the tumor cells, in this case EGFR." (PMID 31705176, 2020). "Heme-dependent dimerization of PGRMC1 has been shown to accelerate tumor growth through the EGFR signaling pathway and facilitate cancer proliferation and chemoresistance." (PMID 32179851, 2020). "Secondly, primary tumour localisation (right/left), a key predictive factor of anti-EGFR therapy, was also excluded from the pooled analysis because there was a lack of information in the ASPECCT cohort." (PMID 32605298, 2020). "The combination of DS-1205b plus erlotinib/osimertinib can effectively inhibit the signaling downstream of EGFR and significantly delay the onset of tumor resistance when compared to monotherapy." (PMID 32549388, 2020). "OPB-51602 had been evaluated in a phase I first-in-human study (NCT01184807), demonstrating promising anti-tumour activity in EGFR-mutant NSCLC with prior EGFR-TKI exposure." (PMID 33092283, 2020). "This study also demonstrated that the suppression of INF-β production was the result of tumour-derived EV EGFR activation of MEKK2 in the recipient macrophages." (PMID 33143170, 2020). "Nanobodies against EGFR fused to TRAIL have shown efficacy against tumor cells resistant to both strategies (inhibition of EGFR and activation of TRAIL) when used separately." (PMID 32528281, 2020). "Epidermal growth factor receptor (EGFR) is commonly expressed on OS cell lines and 90% of primary OS samples, with high expression correlated to large tumor volume, prompting to utilize the anti-EGFR monoclonal antibody cetuximab as a potential therapy." (PMID 33322371, 2020). "In 20% and 31% of the patients, a >50% and >30% decline, respectively, of the serum tumor marker prostate specific antigen (PSA) was reached with a significant improved progression-free survival in patients with EGFR overexpression." (PMID 33260619, 2020). "Recent studies have shown that sensitivity of EGFR ctDNA is lower for tumor tissues, while the data for ALK rearrangement assessment using ctDNA is relatively limited compared with EGFR mutations." (PMID 32974126, 2020). "The present work uncovered a novel mechanism of the tumor suppression by DRAM1: promoting EGFR endosomal-lysosomal trafficking and degradation in NSCLC in vitro and in vivo through interacting with EPS15 and promoting the assembly of lysosomal v-ATPase." (PMID 32943616, 2020). "EGFR protein upregulation, excluding the effect of EGFR gene copy number on protein overexpression, was related to poor differentiation of tumor cells and lymph node metastasis, especially extranodal extension." (PMID 32974098, 2020).
tumor (continued). "Many studies have focused on uncovering the molecular basis of epidermal growth factor receptor (EGFR) activation and its implication in tumor development and progression." (PMID 33050232, 2020). "In summary, aside from blocking EGFR or inducing tumor lysis through the NK cells, nimotuzumab induce specific memory T cells against the EGFR, responsible for long-lasting clinical responses." (PMID 32537431, 2020). "After inputting a mutant EGFR tumor into the deep learning model, the positive filter (the third column of the third line) generated a strong response, while the negative filter (the fourth column of the third line) was nearly shut down." (PMID 33067442, 2020). "The presence of other molecular abnormalities, such as EGFR, KRAS, BRAF or HER2 mutations and ALK rearrangements, has also been identified in some of these tumours." (PMID 31598903, 2020). "Increased rigidity in the tumor stroma favors EGFR activity and results in the calcium-dependent regulation of Cdc42 small GTPase activity in tumor cells." (PMID 32546182, 2020). "Tumor lesions with an EGFR score > 10 had a higher SUVpeak (mean SUVpeak 3.4 for ≤ 10 versus 6.8 for > 10 EGFR score, P = 0.012)." (PMID 31705176, 2020). "In AXL-low-expressing tumor cells, EGFR and IGF-1R bind constitutively and to each protein associated with their adaptor proteins, including Gab1." (PMID 32929081, 2020). "Anti-EGFR Nbs 7D12 have also been used, conjugated with the infra-red fluorophore IRDye800CW, for the optical molecular imaging visualization of human tumor xenograft mouse model, showing a rapid and homogeneous distribution throughout the tumor." (PMID 33353213, 2020). "Kwak et al3 reported patient cases of MET and ERBB2 coamplification occurring in the same tumor cells, including a single case of MET, ERBB2, and EGFR coamplification all occurring within a single tumor cell population." (PMID 32338752, 2020). "Navitoclax plus ABBV-321, an EGFR-targeted ADC that displays more effective wild-type EGFR-targeting, elicited more significant tumor growth inhibition and regressions in the two highest EGFR-expressing models evaluated." (PMID 33256808, 2020). "It was also established that even though genetic suppression of EGFR was found to initially lead to tumor regression and increased animal survival, all tumors eventually recurred and had increased tumor growth." (PMID 35582224, 2020). "Stimulation of this pathway by inhibition of oncogenic mutants of EGFR mediates tumor cell survival in cells lines of lung cancer." (PMID 32179851, 2020). "As inactivation of Psid blocked EGFR signaling-dependent tumor growth, this study raises the possibility that NatB is potentially a novel therapeutic target for cancers dependent on deregulated EGFR/Ras signaling." (PMID 32559195, 2020). "M2 macrophage-like tumor-associated macrophages (TAMs) secreted EGF and then activated EGFR on tumor cells, further up-regulating VEGF/VEGF-R signaling in surrounding tumor cells to finally mediate OC cell proliferation and migration." (PMID 32716025, 2020). "SOCS36E depletion has been reported to potentiate EGFR driven tumor formation by alleviating repression of JAK Stat activity." (PMID 32737065, 2020). "Tumor cells that establish themselves in the neuronal niche upregulate PD-1, EGFR, TOP2A, TOPO1 GABA-R, GLUT-R, TrkB, and P75NTK as well as miRNA expression, mutations, and specific epigenetic changes." (PMID 31900168, 2020). "Here, we demonstrated that epidermal growth factor receptor (EGFR) was highly expressed in tumour tissues of NPC patients with distant metastases and was associated with a decrease in reactive oxygen species (ROS)." (PMID 33304472, 2020).